RRBP1 (ribosome binding protein 1)
Diseases named in the same sentence as RRBP1 in open-access papers (continued):
Sharing a sentence is not in itself a finding about the gene and the disease.
tumor (continued). "In CRC, hsa_circ_0004085 binds RRBP1, stabilizes GRP78, enhances tumor cell adaptation to ERS and promotes drug resistance, thereby inhibiting apoptosis." (PMID 41200062, 2026). "The expression of CSE1L, LOX, RHBDD1, RRBP1 and SOGA1 was significantly higher in tumors than in tumor-adjacent tissue, and the survival analysis of each gene reached the same conclusion." (PMID 36421795, 2022). "Thus, RRBP1 may play a key role in maintaining tumor cell survival under stress conditions." (PMID 34445467, 2021). "Using DNA methylation microarray chip analysis, we identified the membrane protein RRBP1 as a tumor oncogene in UTUC cells, and the potential of RRBP1 as a clinical prognostic marker from The Cancer Genome Atlas (TCGA) BLCA database was further confirmed." (PMID 34445467, 2021). "RRBP1, a receptor for KIF5B, is involved in vesicle transport or mRNA localization of ER origin and its role of combining ribosomes with kinesins suggests its potential involvement in tumor transport or tumor cell invasion processes." (PMID 41200062, 2026). "However, both the tissue specificity of the RRBP1-ALK fusion and the tumor suppressor function of IFITM1 by maintaining it in NFPA caution against a one-size-fits-all solution." (PMID 41200062, 2026). "Real-time PCR analysis showed that the expression of RRBP1 mRNA in tumor sites was lower than that in nontumor sites." (PMID 34445467, 2021). "Ranking of RRBP1 expression according to high to low RRBP1 expression revealed that RRBP1 expression was not correlated with sex, tumor stage, and LVI, but was related to the efficacy of chemotherapy drugs." (PMID 34445467, 2021). "The unusually long 5′ UTR of the RRBP1 protein may form an extensive secondary structure, which possesses IRES activity and, therefore, had several positive effects on tumor cells." (PMID 27447629, 2016). "Furthermore, RRBP1 upregulates epithelial-mesenchymal transition (EMT) genes and basal cell markers and suppresses luminal markers, thus contributing to the acquisition of migratory and invasive properties of tumor cells and a stem cell-like drug-resistant phenotype." (PMID 41200062, 2026). "RRBP1 is markedly upregulated in both early-stage and late-stage cisplatin-resistant OSCC cell lines, as well as in tumor tissues from chemotherapy-non-responsive patients vs. those with chemotherapy-sensitive disease." (PMID 41200062, 2026). "Both USP35 and RRBP1 expression levels were significantly higher in more advanced TNM stages, but were not significantly affected by sex, age, or tumor size." (PMID 34618999, 2022).
cancer (13 papers, 2016 to 2026). A tumor composed of atypical neoplastic, often pleomorphic cells that invade other tissues. "Previous studies with other cancers have demonstrated that RRBP1 is highly expressed in tumors and is associated with poor prognosis." (PMID 34445467, 2021). "Recent studies have shown that the level of RRBP1 is increased in many human cancers and is associated with tumorigenesis, metastasis, and poor prognosis." (PMID 34445467, 2021). "Based on The Cancer Genome Atlas (TCGA) Pan-Cancer Atlas studies, the present review generated an OncoPrint visualization map depicting the types and occurrence frequencies of RRBP1 genetic alterations, while also illustrating the lineage distribution characteristics of specific RRBP1 mutations." (PMID 41200062, 2026). "The present review systematically describes the roles of RRBP1 in cancer, emphasizing its functional diversity." (PMID 41200062, 2026). "It first outlines the structural features and functions of RRBP1, then analyzes its expression and regulatory mechanisms across several cancer types." (PMID 41200062, 2026). "In bone metastasis, RRBP1 secreted by cancer cells exerts a paradoxical role in modulating osteoblast differentiation." (PMID 41200062, 2026). "Knockdown of RRBP1 in cancer cells enhances osteoblast differentiation markers (ALP and bone γ-carboxyglutamate protein), matrix mineralization and bone morphogenetic protein (BMP) 2/SMAD1/5/9 activation in pre-osteoblasts." (PMID 41200062, 2026). "RRBP1 regulates the unfolded protein response by stabilizing glucose-regulated protein 78 and it enhances cancer cell adaptation to endoplasmic reticulum stress and chemotherapy." (PMID 41200062, 2026). "RRBP1 serves complex and key roles in multiple important molecular mechanisms in various types of cancer." (PMID 41200062, 2026). "Despite it is substantially expressed in bone metastatic cancer cells, the role of RRBP1 in regulating the bone microenvironment was obscure." (PMID 36568157, 2022). "All such evidence supports that deregulation of RRBP1 contributes to cancer development and progression." (PMID 34618999, 2022). "Meanwhile, we observed that the protein expression levels of RRBP1 in the two-type cancer cells were higher than that in MC3T3-E1 cells." (PMID 36568157, 2022). "High correlations between RRBP1 and cancer stages, nodal metastasis status, molecular subtypes, and prognosis in bladder urothelial cancer (BLCA) were found." (PMID 34445467, 2021). "The current research report further proves that RRBP1 participates in and promotes the occurrence and development of cancer, but the specific mechanism of action has yet to be elucidated and warrants further research." (PMID 31285390, 2019). "At the same time, we selected 29 cases of cancer tissue specimens and 16 normal tissue specimens for Western blotting and qRT-PCR to study the expression of RRBP1 at the protein and mRNA levels." (PMID 31285390, 2019). "The significance of RRBP1 cancer research is to use the gene as a potential target for cancer therapy." (PMID 31285390, 2019). "Previous studies have shown that RRBP1 is a key player in the initial maintenance of cancer cell survival during conditions such as cellular stress and apoptosis." (PMID 27447629, 2016). "This study was beneficial to gain a better understanding of the IRES-mediated RRBP1 translation mechanism and provide an effective method for cancer therapy." (PMID 27447629, 2016). "To investigate the activity of RRBP1 IRES in cancer cells, we transfected the IRES-containing pRF constructs into Bel7402 and A2780 cell lines and the relative luciferase activities were assayed, respectively." (PMID 27447629, 2016). "RRBP1 has been suggested to be a core molecule mediating the pro-cancer effect of high glucose." (PMID 41200062, 2026). "RRBP1 serves important regulatory roles in cancer genesis and evolution." (PMID 41200062, 2026).
cancer (continued). "Our data suggest that depletion of RRBP1 in bone metastatic cancer cells could boost the osteoblastic phenotype expression, partially through the enhancement of ER stress." (PMID 36568157, 2022). "This study was undertaken to determine whether RRBP1 from bone metastatic cancer cells affects the osteoblastic phenotype expression." (PMID 36568157, 2022). "Moreover, it is reported that elevated RRBP1 closely correlates with cancer progression and poor prognosis." (PMID 34618999, 2022). "It is speculated that the abnormal post-translational modification and protein turnover of RRBP1 may be related to malignant tumor formation." (PMID 34445467, 2021). "The inhibited expression of RRBP1 could potentially reduce the proliferation and metastasis of cancer cell lines." (PMID 34445467, 2021). "Ribosome-binding protein 1 (RRBP1) is a potential oncogene in several cancer types." (PMID 34445467, 2021). "RRBP1 was highly expressed in both malignant tumors and cell lines in clinical specimens." (PMID 34445467, 2021). "The top mutated genes identified in the EGFRvIII-PB tumors were Obscn, Hspg2, Rrbp1, Rpgrip1, and Atp5o which have unknown functions in cancer." (PMID 32727536, 2020). "There is growing evidence that RRBP1 plays a multifaceted role in cancer progression." (PMID 30684972, 2019). "Many studies have explained the mechanism by which RRBP1 promotes the development of cancer." (PMID 31285390, 2019). "Their findings also suggested that RRBP1 may participate in the accumulation of perinuclear autophagosomes in cancer cells by interacting with the kinesin family member 5B (KIF5B)." (PMID 31285390, 2019). "Moreover, GRP78 resisted against ADM-mediated apoptosis in cancer cells, indicating RRBP1 overexpression cells possessed the resistance against ADM." (PMID 27447629, 2016). "IRES activities of XIAP, NRF, and RRBP1 in two cancer cell lines exhibited completely differently." (PMID 27447629, 2016). "However, whether RRBP1 of bone metastatic cancer cells is responsible for modifying the phenotype expression of osteoblasts in the bone microenvironment remains unknown." (PMID 36568157, 2022). "The RRBP1 gene has a low mutation rate in tumors, with no missense or nonsense mutations detected in patients, indicating that its expression in tumors affects the activity of cancer cells, rather than through mutations or deletions." (PMID 34445467, 2021). "Ribosome-binding protein 1 (RRBP1), a core regulator of endoplasmic reticulum-ribosome interactions, serves key roles in the development and progression of various cancer types by coordinating protein synthesis and organelle dynamic interactions." (PMID 41200062, 2026). "Among the genes affected by RRBP1, UBE2C, SHC1, and CLDN7 have all been recently identified as highly relevant targets in other cancers." (PMID 34445467, 2021). "The present results showed that RRBP1 was upregulated in UTUC and promoted the growth of cancer cells." (PMID 34445467, 2021). "It has been reported that RRBP1 also binds to the kinesis protein KFI5B, which is highly expressed in several cancer cell lines." (PMID 31285390, 2019). "In this study, the dual-luciferase plasmid containing RRBP1 mRNA was transfected into several cells and high IRES activity in cancer cells was detected." (PMID 27447629, 2016). "Other genes whose protein products have evidence of function in cancer include RCN3, RRBP1, PDLIM3 and SLC1A4." (PMID 27689402, 2016). "Furthermore, yeast two-hybrid analyses have indicated that the C-terminal region of RRBP1 interacts with the kinesin family member 5B (KIF5B), which has markedly high expression in a variety of cancer cell lines, such as MCF-7, HeLa and U2OS cells." (PMID 41200062, 2026). "We observed the overexpression of isoforms of genes C3orf17, FRMD4A, FZD6, HNRNPA2B1, POSTN, PRKAA1, RRBP1 and VEGFA, and the under expression of TRIP12 isoform (ENST00000428959) in ACC patients who are not free of cancer, which is a surrogate for poor ACC outcomes." (PMID 33035235, 2020).
RRBP1 also shares sentences with these, for which no sentence is quoted: endometrial endometrioid adenocarcinoma (2 papers); liver cancer (2); bladder tumor (1); esophageal cancer (1); fibrosarcoma (1); Flavivirus Infections (1); Hyperglycemia (1); infection (1); mesothelioma (1); neuroblastoma (1); neurodevelopmental disorder (1); non-small cell lung carcinoma (1); osteoporosis (1); ovarian cancer (1); schizophrenia (1); scoliosis (1); thyroid carcinoma (1); uterine carcinosarcoma (1); ZIKV infection (1).